CD44 (CD44 molecule (IN blood group))
Diseases named in the same sentence as CD44 in open-access papers (continued):
Sharing a sentence is not in itself a finding about the gene and the disease.
tumor (continued). "In support of this finding, the CD44+ population from xenograft tumours and cell lines has enhanced proliferative potential and tumour-initiating ability in vivo compared to CD44− cells." (PMID 19040209, 2009). "Future studies will focus on the isolation and characterization of the CD24+/CD44+ and other marker positive tumor subpopulations from HNSCC." (PMID 19602232, 2009). "We next addressed the role of CD44+ cells in initiating tumour recurrences after conventional therapy." (PMID 19240712, 2009). "Small islets of human tumour cells strongly stained for CD44 are visible in the mouse tissue fat pad." (PMID 19240712, 2009). "Here we show for the first time that CD44 targeting with the P245 mAb strongly inhibits the growth of HBCx, suggesting that CD44+ cells play an important role in tumour growth-driving mechanisms." (PMID 19240712, 2009). "It was found that CD44+ cells possessed not only a capacity for forming tumor spheres, proliferation, migration, and invasion in vitro, but also a resistance to chemotherapeutic agents." (PMID 20052382, 2009). "Examples are 'PI3K/AKT', 'KRAS', 'PTEN', 'WNT-beta catenin' and 'MAPK signaling' pathways, as well as a group of genes specific of human tumor initiating cells (CD44+CD24-)." (PMID 19327144, 2009). "In this case, the tumour-initiating cell was AR− and p63− and expressed the stem cell genes Oct-4, Nanog, Sox2, nestin, CD44, CD133 and c-kit." (PMID 19040209, 2009). "These experiments were performed in the absence and presence of a cocktail of antibodies against CD18, CD162 and CD44 to prevent the firm adhesion of the PMN to the tumour cells." (PMID 20169105, 2009). "Is it possible that the CD44+/CD24low/- phenotype is a dynamic one, i.e. can it be lost and de novo acquired during tumor progression, as a result of genetic instability and epigenetic changes?" (PMID 19555472, 2009). "The colocalisation of uPA and CD44 with MDR proteins in tumour cells and stromal cells further highlights the importance of invasive markers in the regulation of drug resistance in the progression of EOC." (PMID 19603017, 2009). "Altered CD44 and other adhesion molecules permit this transition in which tumor cells detach, interact with proteins that digest stromal matrix, migrate through matrix, and intravasate into lymphovascular channels." (PMID 18793421, 2008). "Remarkably, the A1.1 cell line which is derived from 0_A1 tumor showed up to 2.6% CD44+/CD24-/low cells." (PMID 18394172, 2008). "Recently, Wang and colleagues reported that miR-328 is important in regulating tumor development and invasion by targeting CD44 expression in epithelial carcinoma cell lines." (PMID 19002258, 2008). "These previously reported differences in expression of CD24 in different tumor types and in normal mouse mammary epithelium support our search for the role of CD24- cells in combination with a more established marker, CD44, in BRCA1-deficient tumors." (PMID 18241344, 2008). "It has been reported that phosphorylation of the CD44 isoform is required in tumor cell directional sensing of a phorbol ester gradient during invasion." (PMID 18350162, 2008). "CD44+/CD24- tumor cells were detected in 31% (75/240) of the tumors, with the proportion of this phenotype ranging from only a few cells to almost all tumor cells." (PMID 18559090, 2008). "Currently, researches that involved the gene and cytokines such as CD44 and E-cadherin, which were related to tumor metastasis, revealed that the expression level was closely related to the metastatic ability." (PMID 18637206, 2008). "We found that MAP4 and Lrig1 were significantly downregulated in oral SCCs, while CD44, which has recently been reported to be a marker of tumour initiating cells in head and neck SCCs, and MCSP were highly upregulated." (PMID 18657901, 2008).
tumor (continued). "For the specific case of HNSCC, CD44+ CSCs were reported to represent a minority population of less than 10% of the tumour cells in human primary carcinomas and did hold stem cell-like properties, i.e. self-renewal and pluripotency to some degree." (PMID 18852874, 2008). "As anchorage-independent growth is an approximation of tumorigenesis and cancer stem cells are thought to be the tumour-initiating cells, we tested the ability of LNCaP CD44+CD24− cells and CD44+CD24−-depleted cells to form colonies in soft agar." (PMID 18268494, 2008). "Tumours excised from mice injected with either 1000 CD44+CD24− cells or 5 million total LNCaP cells were dissociated, and expression patterns of CD44 and CD24 were analysed by flow cytometry." (PMID 18268494, 2008). "Through its interaction with hyaluronan, CD44 serves as an adhesion molecule in cell–substrate and cell–cell interactions, lymphocyte recruitment to inflammatory sites, and tumor metastasis." (PMID 18350162, 2008). "An important correlation between aberrant alternative splicing and tumor progression has been shown for CD44." (PMID 19516963, 2008). "Through binding all of these ligands, CD44 plays a critical role in initiating the metastatic spread of tumor cells." (PMID 18350162, 2008). "Tumor cells were distinguishable from stromal cells and inflammatory cells (generally CD44+ and CD24-) by expression of cytokeratin clone AE1/AE3 in adjacent sections." (PMID 18559090, 2008). "We also determined the proportion of CD44-/CD24+ and double-positive (CD44+/CD24+) cells in each tumor." (PMID 18559090, 2008). "Tumour formation with DU145 showed an increase in the ability of CD44+CD24− cells to form tumours (5/5) in comparison with CD44+CD24+ cells (3/5)." (PMID 18268494, 2008). "The animal model studies have shown that interfering with the binding of CD44 to its ligand inhibits local tumor growth and metastatic spread." (PMID 18350162, 2008). "Not only does this phenotype identify CoCSC in xenograft tumors, but tumorigenesis can be initiated from primary tumor samples with a small number of ESA+CD44+CD166+ cells." (PMID 18560594, 2008). "To determine the proportion of putative tumorigenic CD44+/CD24- cells within each tumor, we scanned for the presence of Permanent Red staining without any DAB interference." (PMID 18559090, 2008). "To study this relation in more depth, we used five protein markers available for 232 out of the 240 cases with CD44/CD24 data to define five tumor subgroups." (PMID 18559090, 2008). "Alterations in the pattern and efficiency of alternative splicing of several pre-mRNAs (e.g. CD44, BRCA1, WT-1) have been implicated in tumourigenesis and correlated with tumour progression." (PMID 18949081, 2008). "For example, CD44 is a cell-surface glycoprotein that participates in a variety of cellular functions, including tumor metastasis." (PMID 18522751, 2008). "One possible mechanism by which CD44 ligation enhances integrin expression and tumor cell adhesion is through up-regulation of c-Met." (PMID 18350162, 2008). "CD44 is a cell surface glycoprotein that is involved in regulating cell–cell and cell–matrix interactions, migration, and tumour growth and progression." (PMID 17987038, 2007). "CD44-mediated degradation of hyaluronic acid around vessels allows tumour cells expressing the adhesion molecule to enter the flow quickly and develop metastases." (PMID 17222331, 2007). "The inhibition of surface interaction of these proteins by over expression of soluble or truncated CD44 blocked migration and tumor invasion." (PMID 17343740, 2007). "Disruption of CD44/MMP-9 cluster formation, by over expression of soluble or truncated cell surface CD44 reduces tumor invasiveness in vivo." (PMID 17343740, 2007). "CD44 is expressed as a standard receptor (CD44s) and in multiple splice isoforms (CD44v), whose expression is altered during tumour growth and progression." (PMID 17987038, 2007).
tumor (continued). "The expression of VEGF-C (Vascular Endothelial Growth Factor – C), its receptor VEGFR-3 and CD44, were studied on feline mammary samples to assess the importance of lymphangiogenesis and lymphangiotrophism in neoplasia." (PMID 17222331, 2007). "In a complementary study, Abraham and coworkers reported that the prevalence of CD44+/CD24- cells (tumors with >10% of CD44+/CD24- cancer cells) in 22% of tumor samples." (PMID 17062128, 2006). "Second, increase in the interaction of HA with intracellular and surface receptors (CDC37, IHABP, RHAMM & CD44) activates the HA mediated signaling for the active invasive nature of the malignant tumor cells during early stage of tumor progression." (PMID 16401353, 2006). "It is well documented that tumour cells adhere rapidly to the mesothelium both in vivo and in vitro, and a role for the cell adhesion molecule CD44 and the integrins β1, α2, α3 and α5 in mesothelial invasion has been postulated." (PMID 15054468, 2004). "The final multivariate model confirmed the independent prognostic strength of CD44 and suggests an important role for tumour size and histologic grade, even though these two variables failed to attain statistical significance." (PMID 12556966, 2003). "Cellular and tissue CD44 isoform expression patterns have also been widely proposed as markers of tumor growth, metastatic potential, and poor prognosis in several malignancies, including lung cancer." (PMID 19570245, 2002). "Alterations in the pattern and efficiency of alternative splicing of several pre-mRNAs (e.g. CD44, BRCA1, WT-1) have been implicated in tumorigenesis and correlate with tumour progression." (PMID 12087473, 2002). "The expression of CD44 and CD44v6 was determined immunohistochemically on paraffin-embedded tumour samples." (PMID 11161384, 2001). "Eleven of 12 patients with CD44-positive tumours are alive in first remission compared with five of 15 CD44-negative tumours (P = 0.001)." (PMID 10360676, 1999). "Eleven of 20 favourable histology tumours were positive for CD44 compared with one of seven unfavourable tumours (P = 0.07)." (PMID 10360676, 1999). "CD44 isoforms CD44v3, CD44v5, CD44v6 and CD44v7-8 were detected in 28% (20/70), 47% (33/70), 33% (23/70) and 17% (12/70) of the tumour samples respectively." (PMID 9792156, 1998). "CD44 promotes tumor progression by enhancing cell migration, invasion, and metastasis." (PMID 41466485, 2026). "Notably, compared to the control group, the number of total TAMs were not significantly different but were found to be in closer proximity to CD44+ tumor cells with a stem-like phenotype." (PMID 41545340, 2026). "Furthermore, most existing studies have not comprehensively examined how the dense and compositionally complex extracellular matrix, together with the dynamic tumor microenvironment, modulates CD44-mediated nanoparticle transport and therapeutic efficacy." (PMID 41560835, 2026). "Patients who experienced IR or OFP within 12 months (n = 5) trended toward higher CD44 tumor:normal liver RNA expression levels compared with sustained responders (n = 7; median 1.841 vs. 1.295; P = 0.43 using Mann–Whitney), with all patients below background expression achieving SR." (PMID 41411069, 2026). "Its anti-tumor action was mediated primarily by the interaction with CD44." (PMID 41750310, 2026). "Biodistribution studies confirmed CD44-targeted tumor-specific NP accumulation." (PMID 41551982, 2026). "This may be related to the interaction between secreted SPP1 and CD44 on the surface of tumor cells, which activates the PDE3B pathway." (PMID 41056019, 2026). "At the protein level, these organoids contained multiple cellular components, including epithelial cells, mesenchymal cells, K7+ duct cells, a-SMA+ myoepithelial cells, K5+ basement membrane cells, and CD44+ tumor stem cells, with proper spatial distribution patterns." (PMID 41744826, 2026).
tumor (continued). "In an exploratory patient cohort, higher tumor CD44 expression trended with early progression." (PMID 41411069, 2026). "HA is necessary and sufficient to drive clustering of tumor cells expressing its receptor CD44." (PMID 41651843, 2026). "To explore translational relevance, we tested whether tumor CD44 expression would correlate with TARE clinical outcomes in a small exploratory cohort of patients for whom pretreatment tissue was available." (PMID 41411069, 2026). "While CD44 and ALDH1 can identify CSCs, it was found that HNSCC cells having dual expression of both CD44 and ALDH1 HNSCC cells have greater tumourigenic and radiation-resistant attributes and may associate with tumour proclivity." (PMID 40282522, 2025). "In addition to regulating cell proliferation, CD44 promotes tumor cell survival following pharmacological therapy." (PMID 40806710, 2025). "Studies have shown that in kidney renal clear cell carcinoma, the strong interactions between tumor cells and tumor-associated macrophages, driven by MIF and its receptors CD74 and CD44, are critically involved in tumor progression, angiogenesis, and the mechanism of immune evasion." (PMID 40051627, 2025). "CD24 was uniformly expressed, while CD44 levels varied across PF and tumor-derived cells." (PMID 40877861, 2025). "The expression of CD44 isoforms and their expression levels often vary depending on the tumor type." (PMID 39851489, 2025). "The results, analysed using the Mann–Whitney U test, demonstrated a significant reduction in tumour size in the CD44-IR700_IT group when compared to the CD44-IR700_IV group, indicating that the improved efficiency of intratumoural administration was not due to physical damage to the tumour." (PMID 39848206, 2025). "Interestingly, we observed that Ly6G+ S100A8/9+ neutrophils post triple combination surrounded Vim+ CD44+ tumor cells within the liver." (PMID 40568104, 2025). "Moreover, FGFR2 expression was significantly associated with tumor stemness and EMT markers, including CD133, CD44, VIM, and N-cadherin, underscoring the role of the SFRP1-FGFR2 interaction in CRLM." (PMID 40225580, 2025). "Furthermore, the combination therapy increased migratory XCR1+CD103+ dendritic cells (DCs) in tumors and tumor-draining lymph nodes (TDLNs) while expanding CD44+CD8+ T cells with central and effector memory phenotypes." (PMID 40366419, 2025). "Based on this finding, CD44+ may serve as a potential marker for tumor angiogenesis and become an important target for anti-angiogenic therapy." (PMID 40703522, 2025). "CD44 expression may improve exosomal adhesion to hyaluronan present in the tumoral stroma, facilitating exosome penetration and distribution in the tumor microenvironment." (PMID 40806778, 2025). "In malignant tumor cells, the staining pattern and intensity of CD44 were assessed." (PMID 40881916, 2025). "First, we compared tumour microenvironment between the CD44-IR700_IV and CD44-IR700_IT groups." (PMID 39848206, 2025). "Additionally, targeting CD44 with miR-199a has effectively reduced tumor growth in in vitro and in vivo studies, making CD44 an attractive therapeutic target." (PMID 40362280, 2025). "Therefore, CD44 serves as a signaling hub that integrates tumor microenvironmental signals and transmits these signals to signaling pathways involved in tumor progression, including EMT, angiogenesis, cell cycle regulation, and other oncogenic processes." (PMID 40759634, 2025). "Clarke and colleagues found that only cells with a CD44+/CD24low/−ESA+ phenotype had the ability to induce a new tumor with full phenotypic diversity; in turn, the tumor could be sequentially propagated." (PMID 37966629, 2025). "The binding of SPP1 to CD44 on T cells and tumor cells may help maintain an immunosuppressive microenvironment that supports tumor survival and growth." (PMID 41391064, 2025). "Three of these protein panels (including CD44) showed significant increases with tumor progression." (PMID 41440277, 2025).
tumor (continued). "Therefore, CD44 expression indicates an aggressive tumor biology and can serve as an independent marker for prognosis and therapy." (PMID 40881916, 2025). "CD44 regulates the primary functions of CSCs, including cell proliferation, migration, and invasion, as well as the ability to change the extracellular matrix of tissues to encourage new tumor formation." (PMID 40806710, 2025). "In addition, by regulating the expression of the CD44 variant, ESRP1 can also influence critical signaling pathways such as PI3K/AKT and Wnt/β-catenin, thereby participating in the regulation of the tumor microenvironment." (PMID 40046628, 2025). "Furthermore, the immunosuppressive molecule PD-1 displayed different degrees of expression in tumor-specific CD44+CD8+ TIL cells." (PMID 40236705, 2025). "Moreover, SPP1+ macrophages interact with tumor cell CD44, synergizing with RNF32 to enhance cancer stemness via Wnt signaling." (PMID 41387204, 2025). "In addition, studies have shown that CD44 glycoprotein is highly expressed in many tumor tissues and is involved in tumor growth, invasion, and metastasis, with specific binding properties to hyaluronic acid." (PMID 40809017, 2025). "The N‐terminal G1 domain of VCAN, which includes an immunoglobulin (Ig) homolog module and two hyaluronan‐binding domains, binds to hyaluronan and interacts with CD44, stimulating tumor spreading, self‐renewal, and angiogenesis, while reducing matrix permeability." (PMID 40542654, 2025). "CD44 is the most common tumor biomarker used in BC stratification." (PMID 40676293, 2025). "In HER2-amplified tumour models, residual or dormant cells that survive the HER2 blockade are enriched for CD44-positive cells, demonstrating a survival advantage and stem-like phenotype which could help to trigger tumour relapse." (PMID 41463344, 2025). "Additionally, LILRB4 + MM cells communicate with monocytes through the SPP1/CD44 axis, which likely contributes to the regulation of the monocyte–macrophage system within the tumor microenvironment." (PMID 41417876, 2025). "Specifically, platelet‐derived adhesion molecules such as P‐selectin, integrin α6β1, and integrin αIIbβ3 may engage tumor‐associated receptors such as PSGL‐1, CD44, ADAM9, and integrin αvβ3, ultimately promoting active internalization by tumor cells." (PMID 40788220, 2025). "Additionally, markers such as Ki-67, p16, and CD44 offered prognostic information regarding tumor aggressiveness, HPV status, and therapy response." (PMID 40427131, 2025). "Interestingly, the partial EMT phenotype was relatively stable in vivo as shown by the abundance of CD104/CD44/E-cad/VIM positive areas in E/M tumours." (PMID 40764669, 2025). "Comparing the parental tumor core and margin, distinct molecular profiles were revealed, with the tumor margin showing elevated expression of markers such as CD44 and HIF1A, consistency with stemness, hypoxic adaptation, and metabolic reprogramming at the invasive front." (PMID 40431665, 2025). "Additionally, RNA m6A methylation-associated cellular subpopulations within the TME and tumor epithelial cells can participate in many and comprehensive interactions through ligand-receptor pairings, such as MIF-(CD74+CD44)." (PMID 40842994, 2025). "Importantly, CD44+ cells retain the ability to rapidly re-enter the cell cycle upon therapy withdrawal, supporting their potential role as dormant, therapy-resistant tumor cells capable of driving tumor recurrence." (PMID 40430044, 2025). "Tumor-infiltrating T cells with upregulated expression of activation markers, such as CD44, CD69, and CD25, and downregulated expression of exhaustion markers like PD-1 and CTLA-4 indicate a higher T-cell functional status that mediates a stronger and more enduring anti-tumor response." (PMID 40867322, 2025). "Moreover, each tumor type apparently has its own pattern of CD44 expression responsible for migration." (PMID 39851489, 2025).